TNF (tumor necrosis factor)
Diseases named in the same sentence as TNF in open-access papers (continued):
Sharing a sentence is not in itself a finding about the gene and the disease.
depression (continued). "TNFα-levels were not related to depression scores or pain intensity, nor was IL-6." (PMID 34248700, 2021). "Therefore, we speculate that JTW may play a role in the treatment of DM and depression through the key targets such as INS, AKT1, IL-6, VEGF-A, TNF and so on." (PMID 34875999, 2021). "Moreover, other inflammatory markers that were found to be relevantly involved in depression such as IL-1 and TNF-α were not available from the LIFE-Adult-Study; for this reason, only IL-6, CRP and WBC were examined in this work." (PMID 34201276, 2021). "Furthermore, we hypothesized that physical activity would decrease IL-6 and TNF-α more strongly than TAU, resulting in a stronger decrease of the depression severity." (PMID 34204400, 2021). "Factors that are associated with increased non-adherence rates in patients with IBD treated with anti-TNF agents include female gender, smoking, treatment beliefs and illness perceptions, along with psychological comorbidities, especially depression and anxiety." (PMID 33498197, 2021). "A key role of the proinflammatory cytokines IL-6 and TNF-α has in fact been described in depression, moreover, both in patients and experimental models a clear relationship between low levels of BDNF and the presence of anxiety and depression has been suggested." (PMID 34638592, 2021). "In addition, patients with unipolar depression and healthy controls also showed an AUC of 0.74, with 0.69 sensitivity and 0.70 specificity using seven variables (IL-6, carbonyl, BDNF, IL-10, IL-17A, IL-4, and TNF-α)." (PMID 33578686, 2021). "Additionally high TNFα-kynurenine/tryptophan subjects showed enhanced depression severity, anhedonia, and treatment nonresponse." (PMID 34072767, 2021). "According to a study that analyzed the association between circulating cytokine and psychometric scores, TNF-α showed a positive correlation with “tinnitus loudness”, “total perceived stress”, “tension” and “depression”, but negative correlation with “joy” scores." (PMID 34205595, 2021). "Univariate logistic regression models, where depression status was the dependent variable, showed statistically significant associations with fibrinogen, IL-6, CRP and the generalised inflammation factor, but not with TNF-α." (PMID 33064180, 2021). "For example, a meta-analysis of 68 studies found discretely elevated levels of the proinflammatory cytokines IL-6 and TNF-α in acutely ill patients with schizophrenia, bipolar disorder, and major depressive disorder (MDD) compared with non-psychiatrically ill control subjects." (PMID 34650454, 2021). "Taking one step beyond previous studies that evaluated short-term antidepressant treatment responses (up to 12 weeks), we demonstrated the role of higher TNF-α levels as a biomarker for 12-month non-remission and 24-month relapse in patients with depressive disorders." (PMID 34475376, 2021). "We found that baseline TNFα production of PBMC in response to PHA challenge predicted mPT outcomes, and higher logTNFα at T1 (baseline) predicted higher improvement of HADS “depression” (delta HADS “depression” = T2 (discharge) scores—T1 (admission) scores) in the total patient sample." (PMID 33240126, 2020). "Although several pieces of literature had also examined the association between the polymorphism of other cytokine gene and suicidal behavior in major depression disorder (MDD), there is no current research that has analyzed the relationship between TNF-alpha polymorphism and suicide in SCZ." (PMID 31954374, 2020). "Certain serotonin re-uptake inhibitors may alleviate depression, in part because of their effects on cytokines such as interleukin-6 (IL-6) and tumour necrosis factor (TNF)-α, whereas other antidepressants do not appear to reduce cytokine levels." (PMID 31996235, 2020).
depression (continued). "In particular, tumor necrosis factor alpha (TNFα), interleukin-2 (IL-2), interleukin-6 (IL-6), interleukin-13 (IL-13), interleukin-18 (IL-18), C-reactive protein (CRP), chemokine-2 (CCL2), and chemokine-11 (CCL11) are elevated in depression based on multiple meta-analyses." (PMID 32351416, 2020). "Moreover, the MI+ depression model also exhibited similar results to those of the IM group in terms of echocardiography (EF and FS), cardiac markers (CK-MB and LDH), antioxidants (SOD, GSH-Px, and CAT) and inflammatory factors (CRP, IL-6, and TNF-α)." (PMID 32973539, 2020). "This could mean that the correlation between pro-inflammatory cytokines (TNF-α in depressed participants, IL-6 in non-depressed participants) and cognitive fatigue symptoms may not be affected by depression." (PMID 32528052, 2020). "An increase of two well-known pro-inflammatory cytokines, called interleukin (IL)-1β and tumor necrosis factor-α (TNF-α), as well as a decrease of anti-inflammatory cytokines (e.g., IL-10, IL-4, and TGF-β1) have been observed in hippocampus and cortex of animal models of depression and MDD patients." (PMID 32435223, 2020). "Thus, we conducted a systematic review and meta‐analysis, including case–control studies comparing TNF‐α G‐308A in patients with depressive disorders versus controls without psychopathology." (PMID 32307924, 2020). "The results revealed BrainAGE being also correlated to smoking duration (r = 0.20, p < 0.01), alcohol consumption (r = 0.24, p < 0.001), TNFα levels (r = 0.29, p < 0.01), verbal fluency (r = −0.25, p < 0.01), and depression (r = 0.23, p < 0.05), but not to hypertension (p = 0.9)." (PMID 31474922, 2019). "TNFα concentrations were not correlated with the severity of anxiety (Spearman r = 0.15; p = 0.27), depression (Spearman r = 0.18, p = 0.19) or somatization (Spearman r = 0.14; p = 0.28), suggesting that psychological symptoms and CD4+ T-cell stimulated cytokines were not related." (PMID 30842618, 2019). "The potential application of anti-inflammatory agents in depression was tested in a proof-of-principle study with a TNF antagonist which showed that while TNF antagonism did not exhibit generalized efficacy, it improved depressive symptoms in a subgroup of patients with increased inflammation." (PMID 31375659, 2019). "To determine whether chronic systemic inflammation plays a role in the pathogenesis of depression, we compared the serum levels of systemic inflammation biomarkers, i.e., high-sensitivity C-reactive protein (hs-CRP) and tumor necrosis factor-α (TNF-α), between these two groups." (PMID 31233833, 2019). "Also, TNF-α release as an inflammatory marker has been documented in patients with idiopathic major depression additional to circulating interleukin (IL)-1, IL-6, and C-reactive protein (CRP), which correlates with depression severity." (PMID 30866491, 2019). "Our hypothesis was that elderly with depression or Alzheimer’s disease had higher levels of IL-1β, IL-6, TNF-α and CRP than controls without psychiatric disorders." (PMID 30104698, 2018). "In major depression with atypical features, lowered IL-4 but increased IL-2 concentrations were observed, whereas no changes in IL-6 or TNFα concentrations could be established." (PMID 29103192, 2018). "Furthermore, AD patients with depression have even significantly higher levels of IL 6 or TNF α and a lower level of 25-hydroxyvitamin D in circulation than in AD patients without depression." (PMID 28580183, 2017). "Moreover, a significant inverse correlation was observed between serum levels of 25-hydroxyvitamin D and IL 6 (r = - 0.47, p = 0.0048) or TNF α (r = - 0.49, p = 0.002) in AD subjects with depression, but not in AD without depression." (PMID 28580183, 2017).
depression (continued). "We measured the serum levels of IL 6, TNF α and 25-hydroxyvitamin D in age-matched healthy controls (n= 60) and in AD patients without depression (n=26) or AD patients with depression (n=34), and statistically analyzed the changes in these parameters among different groups under this study." (PMID 28580183, 2017). "However, Karaoulanis and colleagues found that serum levels of three cytokines (IL-6, TNF-α, and IL-10) did not significantly change in relation to hot flashes in perimenopausal women with depression." (PMID 28846735, 2017). "In this study, we found that ketamine could attenuate decreased serum levels of IL-1β and IL-6, but not TNF-α level, in rats with depression-like phenotype." (PMID 28600519, 2017). "The relationship between TNFα, cognition, and depression has not been extensively investigated." (PMID 28629481, 2017). "Furthermore, as TNFα and IL4 are also markers of Th1 and Th2 immune pathways respectively, this study suggests a shift away from Th1 responses in favour of Th2 responses, which is in line with previous studies of patients recovering from depression." (PMID 26974430, 2016). "On the other hand, not only proinflammatory cytokines, e.g. tumor necrosis factor-alpha – (TNF-α), the interleukins (IL) and interferon-gamma (IFN-gamma), but also anti-inflammatory cytokines are released by CNS and peripheral-derived immune cells and play a powerful role in depression." (PMID 25880127, 2015). "Psychological conditions, like anxiety and depression, which may cause the fluctuation of TSH, prolactin and TNF-α, were not assessed in the current study." (PMID 25558907, 2014). "In addition, vascular risk factors, including high body mass index level, presence of inflammation markers (e.g., CRP, TNF-α, Hs-CRP, and IL-6), and lack of physical activity, were associated with depression." (PMID 24752391, 2014). "Interestingly, IFN-α produces physiological abnormalities observed in major depressive disorder (MDD): alterations in hypothalamic–pituitary–adrenal (HPA) axis, sleep, monoamines, increased TNF and the development of these abnormalities correlates with the development of depressive symptoms." (PMID 24481186, 2013). "Together with our current data, we hypothesize that in the absence of IL-1ß, depression-like behavior is present only when central TNF-α expression is elevated following the LPS challenge." (PMID 23634700, 2013). "However, it has to be mentioned that in our study there was a trend in increasing levels for TNFα and a trend in decreasing levels for IL-6 in perimenopausal women with depression when compared to perimenopausal women without depression." (PMID 22490187, 2012). "We now propose that SF induces sleepiness via initial and rather selective activation of TNF-α pathways, which then will activate an NADPH-dependent oxidative stress cascade that will ultimately lead to cognitive dysfunction along with anxiety-like behaviors and depression." (PMID 22578011, 2012). "We also found a significant correlation between CIS-induced behavior changes and pro-inflammatory cytokines (IL-6 and TNF-á) and monoamines (5-HT, 5-HIAA and DA), indicating that elevated levels of pro-inflammatory cytokines may function in the development of depression." (PMID 22860054, 2012). "Furthermore, adding the total Manchester COPD Fatigue Scale (MCFS) score, BMI and FFMI to the model did not change the findings; i.e., TNF-α still had a significant positive correlation with BASDEC depression score (Beta = 0.17 p = 0.044)." (PMID 21208443, 2011). "In other words, a high TNFα level in patients with cLBP was not induced by accompanying depression." (PMID 20937109, 2010). "Due to intensive psychotherapy or synergetic effects of exercise and psychotherapy, the depression scores decreased and subjective pain perception, back function, mental composite scale were improved, while TNF-α serum level returned to a level without distinction to healthy controls." (PMID 20937108, 2010).
depression (continued). "To date, no studies have investigated the TNFα profile in coexisting pain and depression." (PMID 20937109, 2010). "However, patients with depression as a comorbidity did not have higher TNF-α levels in comparison to patients without depression." (PMID 20937108, 2010). "Depression as a comorbidity to cLBP did not influence the serum TNFα level." (PMID 20937109, 2010). "At T0, both cLBP patients with (cLBP+DE) and without (cLBP) depression showed significantly higher TNF-α serum levels (P = 0.002 for cLBP+DE, P = 0.004 for cLBP) than healthy controls (HC) that normalized after 10 days of therapy and remained similar to healthy controls." (PMID 20937108, 2010). "Alternatively, the measurements of TNFα concentrations and parenchymal TSPO expression may not provide a comprehensive representation of peripheral or central immune activity associated with depression." (PMID 39657983, 2025). "Materials and Methods: Inflammatory markers (IL-6, IL-1α, and TNF-α) were measured in a sample of 92 patients hospitalized at the Socola Institute of Psychiatry in Iasi, Romania, and compared to a control group with no depression or inflammatory conditions (n = 76)." (PMID 39595067, 2024). "As mentioned in the previous section, pro‐inflammatory cytokines, such as IL‐1β, TNF‐α, IFN‐γ and TGF‐β, can cross the BBB and initiate or modulate astrogliosis, suggesting that stress‐induced exacerbated activation of these glial cells may contribute to depression pathogenesis." (PMID 31421056, 2021). "In addition, anti-inflammatory drugs, such as Celecoxib (a selective COX-2 inhibitor, non-steroidal anti-inflammatory drug) and Etanercept (TNF-α antagonist) may alleviate symptoms of depression." (PMID 34573069, 2021). "Furthermore, in an LPS-induced rat model of depression, administration of ketamine and GTS-21([3-(2,4-dimethoxybenzylidene) anabaseine], a selective α7 nAChR agonist) was shown to reduce the levels of IL-1β, IL-6, and TNF-α compared to the group of rats treated with LPS alone." (PMID 34948222, 2021). "Interestingly, during a one- year study-period, serum levels of IL-6, IL-10, TNF-α, and IFN-γ were significantly higher in the post-stroke depression group relative to a control group, suggesting a relationship between immune dysregulation and post-stroke depression." (PMID 34884906, 2021). "Therefore, immune dysregulation in depressive disorders does not involve exclusively pro-inflammatory cytokines, such as IL-6 and TNF-α, but also activation of anti-inflammatory cytokines, which may result in positive treatment outcomes." (PMID 31375659, 2019). "Proinflammatory cytokines, such as TNF-a, IL-1, and IL-6, are the major mediators between the brain, HPA axis, and immune system and continuous prolonged upregulation of proinflammatory cytokines can lead to depression and HPA axis suppression, which may trigger exacerbation of asthma." (PMID 28740537, 2017). "In a third of patients with depression, the serum and cerebrospinal fluid (CSF) concentrations of inflammatory markers in serum showed the elevation of pro-inflammatory factors such as interleukine (IL)-6, tumor necrosis factor (TNF)-α, and C-reactive protein compared to non-depressed patients." (PMID 27065808, 2016). "Many observation have shown that effects of the cytokine system, in which TNF-α is a part, on serotonin metabolism as well as on the hypothalamic-pituitary-adrenal (HPA)-axis, may induce changes in the structure and function of the brain, possibly leading towards the development of depression." (PMID 27187381, 2016). "However, it should be noted that for serum levels of TNFα there is an increasing trend and for levels of IL-6 there is a decreasing trend in the two subgroups of perimenopausal women with depression (treated and not treated with SSRIs) when compared to perimenopausal women without depression." (PMID 22490187, 2012).
depression (continued). "In a different study, a negative correlation between the expression of TNF RI or TNF RII and working memory was observed in healthy subjects (n = 69) and patients with depression (n = 89)." (PMID 41153321, 2025). "In an early TNF inhibitor (TNFI) trial, depression improvement was not correlated with objective improvement in skin signs." (PMID 39959848, 2025). "In particular, about depression, there is growing evidence of a link between ACE and depression as adults, which is mediated by inflammation, recorded through increased IL-6 and TNF-α, but not by PCR." (PMID 40141399, 2025). "Clinical evidence has demonstrated significantly higher concentrations of inflammatory cytokines, such as IL-1β, IL-6 and TNF-α activated by NLRP3 in the cerebrospinal fluid and serum of patients with depression compared to non-depressed individuals." (PMID 37474898, 2023). "Anxiety/depression symptoms were found to be significantly related to steroid resistance, but independent of AZA/6-MP and anti-TNF agents nonresponse." (PMID 37547213, 2023). "This was most notable in subjects who experienced a clinically significant improvement in depression where they had significant decreases in IL‐6, CRP, and tumor necrosis factor alpha (TNF‐α) compared to those who experienced no improvement in depression." (PMID 36178333, 2023). "In our results, cancer patients with depression exhibited higher levels of inflammatory cytokines (IFN-γ, TNF-α, and IL-6), as compared to the cancer patients without any depression." (PMID 37153524, 2023). "A previous study identified increases in serum cytokines associated with innate immune activation in FEP when compared to healthy controls; however, TNF-α and IL-4 were elevated further in FEP patients with depression compared to those without depression." (PMID 36463221, 2022). "In addition, research on major depressive disorder (MDD) revealed that C-reactive protein (CRP) could serve as a marker of neuroinflammation and peripheral inflammation and is well-suited for guiding immunotherapy targeting inflammatory cytokines such as TNF-α and IL-6 in the patient with MDD." (PMID 35783147, 2022). "This negative result is discordant with several studies and meta-analyses showing higher levels of some immune factor in patients with depression compared to non-depressed controls, such as C-reactive protein (CRP), IL-6, and TNF-alpha." (PMID 34741019, 2021). "In a recent study in a mouse model of depression, CBD reduced both serum and prefrontal cortex IL-6, but not TNF-α,12 h after LPS administration." (PMID 33984046, 2021). "Finally, these findings accord with the growing consensus that TNFα, IL-6 and CRP are among the important biomarkers with translational potential in mood disorders, suggesting that this may be true in the psychological as well as pharmacological treatment of depression." (PMID 33276697, 2020). "Of these, fRG more strongly, but not significantly, alleviated IS-induced depression-like behaviors in FST and TNF-α expression in the colon than RG." (PMID 32224881, 2020). "In the following step, we performed binomial logistic regression analyses, contrasting miRNA expression levels by disease state (HD or healthy volunteer) and adjusting for depression, DST non-suppression status, CTQ total and TNF-alpha as co-variates." (PMID 31542994, 2020). "Serum levels of proinflammatory cytokines, such as tumor necrosis factor-α (TNF-α), are also higher in patients with depression than in those without depression or anxiety." (PMID 31233833, 2019). "In conclusion, our meta-analysis found that elderly with depression had elevated peripheral levels of IL-1β, IL-6 but not CRP and TNF-α, and elderly with Alzheimer’s disease only had increased peripheral levels of blood IL-1β." (PMID 30104698, 2018).